SBF2 (SET binding factor 2)
Description:
Guanine nucleotide exchange factor (GEF) which activates RAB21 and possibly RAB28. Promotes the exchange of GDP to GTP, converting inactive GDP-bound Rab proteins into their active GTP-bound form. In response to starvation-induced autophagy, activates RAB21 which in turn binds to and regulates SNARE protein VAMP8 endolysosomal transport required for SNARE-mediated autophagosome-lysosome fusion. Acts as an adapter for the phosphatase MTMR2 (By similarity). Increases MTMR2 catalytic activity towards phosphatidylinositol 3,5-bisphosphate and to a lesser extent towards phosphatidylinositol 3-phosphate (By similarity).
Synonyms: CMT4B2; KIAA1766; MTMR13; DENND7B
Tractability: Antibody: UniProt places it where antibodies can reach, with high confidence. PROTAC: ubiquitination databases record sites on it; its protein half-life has been measured.
Gene: Protein-coding gene on chromosome 11 (9,776,776 to 10,304,877, reverse strand). Ensembl gene ENSG00000133812.
Subcellular location: Cytoplasm; Cytoplasm, perinuclear region; Membrane; Endosome membrane; Cell projection, axon
Subcellular location (Human Protein Atlas): Nucleoplasm; Cytosol; Intermediate filaments
Pathways (Reactome):
Metabolism: Synthesis of PIPs at the plasma membrane
Vesicle-mediated transport: RAB GEFs exchange GTP for GDP on RABs
Gene Ontology:
Molecular function: guanyl-nucleotide exchange factor activity; protein binding; identical protein binding; phosphatase binding; phosphatase regulator activity; phosphatidylinositol binding
Biological process: myelination
Cellular component: cytoplasm; membrane; cytosol; endosome membrane; axon; perinuclear region of cytoplasm; vacuolar membrane
Genetic constraint (gnomAD): Loss-of-function variants: 85 observed, 172.19 expected, observed/expected ratio (o/e) 0.49, 90% interval 0.41 to 0.59. The upper end of that interval is the gene's LOEUF score, 0.59, which puts it in group 2 of 6, group 1 being the genes least tolerant of losing a copy. Missense variants: 1,648 observed, 1,911.9 expected, observed/expected ratio (o/e) 0.86, 90% interval 0.83 to 0.9. Synonymous variants: 627 observed, 679.49 expected, observed/expected ratio (o/e) 0.92, 90% interval 0.86 to 0.99.
Gene-disease validity (ClinGen):
ClinGen rates the evidence that SBF2 causes each of these diseases.
Charcot-Marie-Tooth disease type 4B2 (autosomal recessive): Definitive.
Homologues: Orthologues: chimpanzee SBF2 (99% identical), macaque SBF2 (99% identical), dog SBF2 (96% identical), rabbit SBF2 (95% identical), guinea pig SBF2 (94% identical), mouse Sbf2 (94% identical), rat Sbf2 (94% identical), pig SBF2 (93% identical), tropical clawed frog sbf2 (80% identical), zebrafish sbf2 (73% identical), Drosophila melanogaster Sbf (44% identical), Caenorhabditis elegans mtm-5 (23% identical), and 10 more. Paralogues in human: SBF1 (59% identical), MTMR3 (12% identical), MTMR4 (11% identical), MTMR2 (10% identical), MTMR1 (10% identical), MTM1 (10% identical), MTMR7 (10% identical), MTMR6 (9% identical), MTMR8 (9% identical), MTMR10 (8% identical), MTMR9 (8% identical), MTMR12 (8% identical), and 1 more.
Diseases named in the same sentence as SBF2 in open-access papers:
SBF2 is named in the same sentence as 32 diseases in open-access papers, as found by Europe PMC text mining. Sharing a sentence is not in itself a finding about the gene and the disease. The quoted sentences say what the papers report.
glaucoma (8 papers, 2008 to 2024). Increased pressure in the eyeball due to obstruction of the outflow of aqueous humor. "Variants in SBF2 are known to be associated with Charcot-Marie-Tooth disease type 4B2 accompanied by early-onset glaucoma (CMT4B2, MIM: 604563)." (PMID 38755526, 2024). "CMT4B1 (MIM 601382) is caused by mutations in the myotubularin family member MTMR2, whereas CMT4B2 (MIM 604563), which can also feature glaucoma, is caused by mutations in MTMR13 (SBF2), which encodes a phosphatase-dead myotubularin-related protein that interacts directly with MTMR2." (PMID 31413155, 2019). "From 21 glaucoma disease-associated genes with measurable expression, 2 were upregulated (MYOC and FOXE3) and five were downregulated (SH3PXD2B, NF1, SBF2, ADAMTS17, and FOXC1)." (PMID 35348588, 2022). "Mutations in the MTMR13/SBF2 gene, which encodes a catalytically inactive member of the myotubularin family involved in heterodimerization with MTMR2, cause CMT4B2 (OMIM 604563), which has similar pathological features to CMT4B1, with additional glaucoma in some patients." (PMID 18429927, 2008).
Charcot-Marie-Tooth disease (7 papers, 2013 to 2025). An inherited degenerative disorder involving the peripheral nerves. "Our whole-genome sequencing analyses initially highlighted Sbf2 – the gene associated with Charcot-Marie-Tooth disease in humans – as a strong candidate, with segregation patterns consistent in one pedigree." (PMID 41282141, 2025).
neuropathy (7 papers, 2012 to 2022). A disorder affecting the nervous system that manifests with pain, tingling, numbness, and/or muscle weakness. "Particularly, subgroups of patients in which neuropathy is markedly more common, such as those of African descent, are likely to benefit from identifying the presence of SBF2 variants preemptively." (PMID 34986146, 2022). "Our data points to a convergence on inflammation as a mediator of increased risk of taxane-induced neuropathy in the face of low SBF2 expression." (PMID 34986146, 2022). "Mutations in MTMR2 and MTMR13 (also called SET-binding factor 2) cause the demyelinating CMT4B1 and CMT4B2 neuropathies respectively with early-onset glaucoma." (PMID 28553203, 2017).
Charcot-Marie-Tooth disease type 4B2 (3 papers, 2022 to 2024). "SBF2 mutations cause Charcot-Marie-Tooth disease type 4B2 (CMT4B2), a sensorimotor neuropathy; CMTs share similar features including a demyelinating neuropathy associated with reduced nerve conduction velocity and focally folded myelin." (PMID 36005139, 2022). "We have previously identified the association of developing severe TIPN with gene SBF2, which is a gene known for causing an inherited neuropathy, Charcot-Marie-Tooth disease type 4B2." (PMID 34986146, 2022). "SBF2 is a biologically plausible candidate gene to investigate in the context of TIPN due to its involvement in a similar pathology, the autosomal recessive polyneuropathy, Charcot-Marie-Tooth Disease Type 4B2 (CMT4B2)." (PMID 34986146, 2022).
demyelinating peripheral neuropathy (2 papers, 2019 to 2022). "Either the lipid phosphatase MTMR2 or its regulatory binding partner, MTMR13/SBF2, has been related to the demyelinating peripheral neuropathy CMT disease type 4B (CMT4B)." (PMID 36106167, 2022).
polyneuropathy (2 papers, 2016 to 2020). A disease or disorder affecting more than one nerve. "A genetic variant of MTRM13/SBF2 has been identified as causative in affected Miniature Schnauzers with this polyneuropathy." (PMID 32738000, 2020). "SBF2 encodes for a gene that, when mutated, is known to be associated with a subtype of Charcot-Marie-Tooth (CMT), a known hereditary form of polyneuropathy that develops in adolescence, early adulthood, or middle age." (PMID 27732968, 2016).
Thrombocytopenia (2 papers, 2019 to 2021). A reduction in the number of circulating thrombocytes. "The finding of this mutation in the SBF2 gene may refer to the cause of thrombocytopenia in humans." (PMID 34946969, 2021). "For example, in humans, a variant within the dDENN domain of SBF2 leads to a demyelinating neuropathy and a variant within the DENN domain causes a thrombocytopenia without neurological manifestations." (PMID 31772832, 2019).
Anxiety (1 paper, 2016). Intense feelings of nervousness, tension, or panic often arise in response to interpersonal stresses. "Another interaction was between UT-Other and a SNP upstream of the SBF2/ADM genes; SBF2 was associated with addiction, and ADM was associated with anxiety, depression and bipolar disease." (PMID 28002425, 2016).
breast carcinoma (1 paper, 2022). "Through whole-exome sequencing (WES), we identified the association of five rare variants in SET-Binding Factor 2 (SBF2) with an increased risk of TIPN in AA patients in the randomized phase III adjuvant breast cancer trial, ECOG-ACRIN-5103." (PMID 34986146, 2022). "To this end, we are conducting an NCI-sponsored ECOG-ACRIN clinical trial, EAZ171 (NCT04001829), to prospectively test whether breast cancer patients of African descent with germline SBF2 mutations do indeed have higher rates of TIPN." (PMID 34986146, 2022).
colorectal cancer (1 paper, 2015). A primary or metastatic malignant neoplasm that affects the colon or rectum. "The aim of this study was to investigate the relationship between CHCHD3P1-HSP90AB7P, GRID1, HSPA12A, PRLHR, SBF2, POLD3, and C11orf93-C11orf92 genes and susceptibility to gastric and colorectal cancers in the Chinese Han population." (PMID 26302849, 2015). "The aim of this research was to study whether polymorphisms of CHCHD3P1-HSP90AB7P, GRID1, HSPA12A, PRLHR, SBF2, POLD3 and C11orf93-C11orf92 genes are associated with the risk of gastric and colorectal cancers in the Chinese Han population." (PMID 26302849, 2015).
glioblastoma (1 paper, 2024). The most malignant astrocytic tumor (WHO grade IV). "For instance, lncRNA SBF2 (SET binding factor 2) induces temozolomide resistance in glioblastoma cells during chemotherapy." (PMID 37994401, 2024).
Hypertension (1 paper, 2026). The presence of chronic increased pressure in the systemic arterial system. "However, we identified novel genes (SBF2, ARHGAP12, EPAS1, CLEC16A, and LRPPRC) to be associated with hypertension." (PMID 41898884, 2026).
oral cancer (1 paper, 2020). "In addition, interference with SBF2 expression can inhibit the proliferation and invasion of human oral cancer cells and induce apoptosis, suggesting that the role of SBF2 gene can be determined by inhibiting the TGF-β pathway." (PMID 32655617, 2020).
pancreatic adenocarcinoma (1 paper, 2015). "In both population that included cases of European descent and in a combined analysis with cases from China, SNPs in the SBF2 gene were associated with survival time among patients with pancreatic adenocarcinoma." (PMID 26302849, 2015).
pancreatic cancer (1 paper, 2020). "For instance, loss of lncRNA SBF2-AS1in M2 macrophage-derived exosomes can elevate miR-122-5p to reduce XIAP and repress pancreatic cancer." (PMID 33552977, 2020).
sensory ataxia (1 paper, 2025). Any ataxia in which the causes of the disease is a perturbation of the sensory system, leading to its dysfunction. "Other significant clinical clues in demyelinating CMT subtypes included vocal cord paralysis in GDAP1, ophtalmoparesis and tongue fasciculations in FGD4, severe sensory ataxia in PRX, respiratory involvement in MTMR2 and SBF2, similar to previous reports." (PMID 39776111, 2025).
peripheral neuropathy (5 papers, 2016 to 2025). A disorder affecting the peripheral nervous system. "Although the role of SBF2 remains poorly characterized, it has been associated with taxane-induced peripheral neuropathy." (PMID 40863222, 2025). "In conclusion, we have identified a splicing variant in SBF2 as the most likely cause for the demyelinating peripheral neuropathy observed in Miniature Schnauzer dogs." (PMID 31772832, 2019).
neurodegenerative disease (1 paper, 2013). A disorder of the central nervous system characterized by gradual and progressive loss of neural tissue and neurologic function. "Other human neurodegenerative disease-related genes sharing a PH/RhoGEF domain, such as DNM2, SBF2, and ALS2, could provide important clues for these elusive questions." (PMID 23844677, 2013).
SBF2 also shares sentences with these, for which no sentence is quoted: X-linked centronuclear myopathy (4 papers); centronuclear myopathy (2); anemia (1); cancer (1); Charcot-Marie-Tooth neuropathy (1); demyelinating (1); depression (1); hereditary motor and sensory neuropathy (1); neurological disorders (1); neuromuscular disease (1); Onset (1); ovarian carcinoma (1); Sensorimotor neuropathy (1); Vocal cord paralysis (1).